IL1B (interleukin 1 beta)
Diseases named in the same sentence as IL1B in open-access papers (continued):
Sharing a sentence is not in itself a finding about the gene and the disease.
Obesity (continued). "Given that both the NLRP3 and NLRP1 inflammasome produce mature caspase-1 to cleave IL-18 and IL-1β, how these opposing effects occur, and in which cellular compartments, to drive or limit obesity remain unanswered questions that will be important to resolve." (PMID 29515457, 2018). "IL-1β is a pro-inflammatory cytokine and increased concentrations of IL-1β have been observed in obese individuals, and animals with diet-induced obesity." (PMID 30400947, 2018). "In some tissues, advanced glycation end products (AGEs), which accumulate in NP tissues and promote its degeneration, increase oxidative stress and IL‐1β secretion, resulting in disorders, such as obesity, diabetes mellitus and ageing." (PMID 28224704, 2017). "Reduced IL-1β secretion and caspase-1 activation; inhibited diet-induced IL-1β and caspase-1 expression from obesity, NASH, adipose tissue inflammation, and insulin resistance." (PMID 29312290, 2017). "We conclude that Th17 cell-derived cytokines participate in the deleterious processes leading to adipose tissue dysfunction in obesity, albeit more modestly than IL-1β." (PMID 28592801, 2017). "Although IL-17 contributes to these cellular alterations, our data point towards a markedly more potent effect of IL-1β, adding further support for its role of “master” regulator of adipose tissue dysfunctional state in human obesity." (PMID 28592801, 2017). "While an increasing number of adipokines are implicated in the development of the obese phenotype, the focus of this review will include MCP-1, IL-6, TNF-α, IL-1β, leptin and adiponectin as the key mediators of AT inflammation and dysfunction in obesity." (PMID 29186929, 2017). "Although obesity-induced low inflammatory status is a result of a combination of multiple factors, our study provides a partial basis for the role of IL1β in obesity and reproduction." (PMID 28373640, 2017). "The increase of the proinflammatory plasma cytokines TNF-α and IL-1β as well as the decrease of the anti-inflammatory plasma cytokine IL-10 displayed the low-grade inflammation status which is well known in obesity." (PMID 28357137, 2017). "One study showed that obesity is associated with increased salivary level of CRP, while another study showed that IL-1β concentration in saliva is associated with periodontal disease severity rather than diabetes." (PMID 28253297, 2017). "In the present study, calpain inhibition reduced obesity-induced pro-inflammatory gene expression including TNFα, IL-6, and IL-1β in adipose tissue." (PMID 29089532, 2017). "As obesity is also considered an inflammatory disease, we also assessed the blood levels of pro-inflammatory cytokines IL-1β and TNFα." (PMID 28744254, 2017). "With obesity, PTX3 mRNA expression is elevated in adipose tissue and is positively associated with the mRNA expression of the proinflammatory cytokines interleukin-1 beta (IL-1β) and tumor necrosis factor alpha (TNF-α)." (PMID 28400677, 2017). "Another study in individuals revealed that, during obesity, elevated levels of C-reactive protein and interleukin (IL)-1β in the blood were predictive indicators of the development of T2D." (PMID 29096724, 2017). "The results revealed that more than 70% of the patients suffering from NDs, depression, and obesity, had decreased expression of both IL-1β and IL-6 (P < 0.001)." (PMID 29736225, 2017). "In the murine model of obesity, the expression level of inflammatory markers including IL-1β and TNF-α as well as the macrophage marker CD68 was significantly enhanced in metabolic organs, together with CypB." (PMID 29312150, 2017). "IL-1β is not only a key contributor to obesity-induced inflammation and subsequent insulin resistance but also type 2 diabetes." (PMID 26881256, 2016). "Nowadays, obesity is considered chronic, low-grade inflammation, with excess production of IL-1β, Il-6 and TNF-α." (PMID 27097934, 2016).
Obesity (continued). "Recent reports suggest that activated ceramide induces caspase-1 activation, IL-1β production in an Nlrp3 inflammasome dependent mechanism in obesity or acute lung injury." (PMID 26980705, 2016). "In obesity, macrophages infiltrate adipose tissue and begin to induce proinflammatory cytokines, such as IL-1β, TNFα, and IL-6, which contribute to insulin resistance." (PMID 27066503, 2016). "IL-17A can induce expression of TNF-α, IL-6, and IL-1β cytokines, which are found with increased levels in obesity." (PMID 27070576, 2016). "IL-22 amplifies IL-1β driven inflammation in human adipose tissue, thereby disrupting glucose homeostasis in obesity and T2DM." (PMID 27829708, 2016). "Systemic inflammation can increase during obesity, resulting in increased proinflammatory cytokines such as IL-1β and TNF-α, which induce muscle wasting." (PMID 27579157, 2016). "In obesity, macrophages infiltrate adipose tissue and begin to induce proinflammatory cytokines, such as interleukin-1 beta (IL-1β), tumor necrosis factor alpha (TNFα), and interleukin-6 (IL-6), which can interfere with insulin signaling in adipocytes." (PMID 27066503, 2016). "NLRP3 has been recently shown to play a key role in the pathogenesis of insulin resistance and obesity, and is regulated by compounds such as ceramide, which induce IL-1β processing via caspase-1 activation." (PMID 27812198, 2016). "In obesity, inflammatory mediators such as IL-1β, TNF-α, and interferon gamma can elevate the CCR6 expression level." (PMID 27869712, 2016). "The pro-inflammatory cytokines TNFα, IL-1β, and IL-6, considered as highly involved in obesity-related IR and the anti-inflammatory cytokines IL-4 and IL-10 displayed similar levels in CT, OIS, and OIR subjects." (PMID 27111539, 2016). "There are two types of evidence indicating obesity as a chronic inflammatory illness: the release of proinflammatory cytokines such as TNFα, IL-6 and IL-1β from adipose tissues and infiltration of macrophages into the WAT." (PMID 26347815, 2015). "Interleukin-1 receptor-1 (IL1R1) and its ligand, IL1β, are upregulated in cardiovascular disease, obesity, and infection." (PMID 25949827, 2015). "While concentrations of TNF-α and IL-1β appeared to be elevated in certain subgroups of patients, the role of confounding factors, such as age and obesity, should be taken into account when planning future research on these immune markers." (PMID 26065825, 2015). "Type 2 diabetes, hypertension, dyslipidemia and increased values of waist circumference, body fat, leptin, fibrinogen, IL-1β, hsCRP and TNFα were related to obesity (p < 0.05)." (PMID 25897330, 2015). "Obesity, specifically abdominal or visceral obesity, leads to high levels of pro-inflammatory adipokines including IL–6, IL–1β, leptin and TNF-alpha." (PMID 26437377, 2015). "Early during infection (i.e., d3 p.i.), obesity was again associated with reduced production of cytokines IL-13, IL-5, IL-12p70, IFNγ, TNFα, IL6, and IL-1β, as well as IL-28b (IFNλ), IL-17, and IL-15." (PMID 26110868, 2015). "Other inflammatory markers such as interleukin-1 receptor-1 (IL1R1) and its ligand, IL1β, are upregulated in cardiovascular disease, obesity, and infection." (PMID 25949827, 2015). "Obesity causes hypertrophy of adipose tissue that leads to the release of diverse inflammatory cytokines, such as TNF-α and IL-1β, and these increased cytokines lead to insulin resistance through the inhibition of the insulin receptor signaling pathway." (PMID 26569269, 2015). "Activation of caspase-1 is required for optimal IL-1α and IL-1β maturation and secretion, with growing evidence implicating uncontrolled caspase-1 activation to be responsible for the pathophysiology of obesity and type 2 diabetes." (PMID 25849717, 2015). "Recently, it has been assessed that IL-1β is an instigator of the pro-inflammatory response in obesity via production of additional pro-inflammatory cytokines, such as IL-6." (PMID 25548896, 2014).
Obesity (continued). "IL-1β plays a key role in obesity-induced inflammation and inflammation-related carcinogenesis by modulating the gene expression involved in proliferation, survival, and angiogenesis." (PMID 25515685, 2014). "We used human adipose tissue biopsies to study the relationship of MAP3K8 expression with markers of obesity and expression of pro-inflammatory cytokines (IL-1β, IL-6 and IL-8)." (PMID 24586913, 2014). "To investigate these relationships and their potential interactions, we first examined the effects of experimentally-induced low testosterone and obesity on brain levels of two established pro-inflammatory markers, TNFα and IL-1β." (PMID 25224590, 2014). "Our data demonstrate that low testosterone and obesity independently increased cerebrocortical mRNA levels of both TNFα and IL-1β." (PMID 25224590, 2014). "The balance of IL-1β and IL-1Ra is particularly important and as IL-1β expression increases with obesity it induces the expression of IL-1Ra." (PMID 25244011, 2014). "IL-1Ra is a naturally occurring inhibitor of IL-1β, and it is upregulated in obesity and reduced in poorly controlled T2D patients." (PMID 25167060, 2014). "IL-1β is also released by human adipose tissue explants but is due primarily to the nonfat cells, and the levels released are enhanced in obesity." (PMID 24918199, 2014). "Knock out models suggest that abolition of IL-1β or its receptor IL-1R1 partially protects against obesity-induced metabolic disease." (PMID 23844177, 2013). "Obesity is associated with a state of chronic or low grade systemic inflammation which increases production of obesity-related inflammatory cytokines, such as IL-1β, IL-6, TNFα, leptin and decrease anti-inflammatory cytokine levels, such as adiponectin." (PMID 24143244, 2013). "To determine if adipose-derived IL-1β can directly regulate fat-liver communication or rather act locally to alter adipose tissue adaptation in obesity, we utilized co-culture of primary hepatocytes with adipose tissue explants." (PMID 23341960, 2013). "To begin addressing the local role of IL-1β in adipose adaptation to diet-induced obesity, we tested the effect of HFF on adipose tissue expression of pro-inflammatory cytokines in IL-1βKO mice." (PMID 23341960, 2013). "Related to obesity and type 2 diabetes, circulating levels of IL-1β were demonstrated to predict Type 2 diabetes when in conjunction with circulating IL6, suggesting a potential role for circulating IL-1β levels (though not as sole factor)." (PMID 23341960, 2013). "The Nod-like receptor family, pyrin domain-containing 3 (NLRP)-3 inflammasome complex plays an instrumental role in the activation of IL-1β during obesity." (PMID 23921145, 2013). "Collectively, the adipose tissue response to HFF in IL-1βKO mice uncovers a major role for IL-1β in the development of adipose tissue inflammation in response to diet-induced obesity." (PMID 23341960, 2013). "Rather, adipose-derived IL-1β seems to act primarily locally to regulate adipose tissue adaptation to obesity, consequently resulting in impaired fat-liver crosstalk." (PMID 23341960, 2013). "Previous studies have demonstrated local effects of IL-1β on either adipocytes or hepatocytes, both of which can contribute to hepatic lipid accumulation in obesity: In cultured adipocytes IL-1β was shown to induce lipolysis by down-regulating PPARγ." (PMID 23341960, 2013). "Resistin and the proinflammatory cytokines, such as TNF-α, IL-6, and IL-1β, produced by adipocytes, and macrophages, are considered to be important modulators of chronic inflammation contributing to the development of obesity and atherosclerosis." (PMID 23484124, 2013). "A collection of recent studies have identified the NLRP3 inflammasome as a central sensor that detects obesity-related stress signals and that triggers IL-1β production and subsequent disease pathogenesis." (PMID 23087690, 2012).
Obesity (continued). "Obesity was associated with inflammation in the mouse mammary gland and was accompanied by elevated levels of TNF-α, IL-1β, and COX-2 in both the mammary gland and visceral fat." (PMID 23272114, 2012). "Of note, obesity progression in both diet-induced and genetically prone obese mice coincided with enhanced caspase-1 and IL-1β activity." (PMID 23087690, 2012). "IL-1β has been recently recognized as a potent instigator of the obesity-induced inflammation and as such a contributor to IR." (PMID 22765047, 2012). "The high levels of NA and IL-6 (and IL-1β) found in obese animals may reflect defective regulation of the negative inflammatory/stress feedback loop in MS - a physiological state that may in turn be either the cause or the consequence of the diabetes associated with obesity." (PMID 21599899, 2011). "In diet-induced obesity, macrophages infiltrate into white adipose tissue and these infiltrated macrophages produce inflammatory markers such as IL-1β." (PMID 21388548, 2011). "Compared with a number of reports on the role of IL-1β as an endogenous mediator of insulin resistance, studies on the relationship between IL-1α and insulin signaling and obesity are rare." (PMID 22216303, 2011). "Of note, the pathophysiological link between obesity and resulting T2D mediated by IL-1α, IL-1β, and their antagonist IL-1ra is discussed in current literature, but is not completely understood." (PMID 20169140, 2010). "Hyperleptinaemia is observed frequently in obesity due to leptin resistance, and high levels of IL-1b and other inflammatory mediators are also a common finding in patients with obesity and metabolic syndrome." (PMID 20798765, 2010). "The confounding factor-adjusted odds ratios (OR) and 95% confidence intervals (CI) for obesity were calculated for each IL-1B C-31T genotype by using unconditional logistic regression analysis." (PMID 19398847, 2009). "Together, these findings suggest that irisin may serve as an associative biomarker for identifying individuals at risk of obesity-related metabolic disturbances, whereas CCL2 and IL-1β may be more indicative of chronic adipose tissue inflammation." (PMID 42196825, 2026). "In general, the G2 subgroups with obesity showed higher levels of pro-inflammatory cytokines IL-1β, IL-6, IFN-γ, and TNF-α than the respective G1 subgroups, and also an association of CMI in favor of a pro-inflammatory systemic status, particularly in the older women group." (PMID 41602164, 2026). "On the contrary we do find inflammatory cytokines like IL-1β which shows an association with diabetes type 2 but not obesity while IL-6 is more closely associated with obesity than diabetes." (PMID 41710408, 2026). "While meta-analyses do not show a consistent reduction in IL-1β levels in response to exercise, a sub-analysis indicates that combining aerobic and resistance training significantly lowers IL-1β in individuals with overweight/obesity and cardiometabolic diseases." (PMID 40595707, 2025). "However, IL-1β concentrations were higher in women with obesity compared with those of normal weight at 28 GW (127.1 vs 89.4 fg/mL, P = 0.038)." (PMID 40886951, 2025). "Interleukin 1-beta is one of the major proinflammatory cytokines, and its increased concentration is found in testes in a variety of systemic or local pathological processes, e.g., obesity, ischemia/reperfusion injury, or some drugs, such as methotrexate." (PMID 40283981, 2025). "Moreover, pro-inflammatory cytokines can contribute to skeletal muscle disorders, such as sarcopenia, presenting similar elevated inflammatory markers as obesity, like interleukin-1β (IL-1β), IL-6 and tumor necrosis factor alpha (TNF-α)." (PMID 41141350, 2025).
Obesity (continued). "One possible explanation is that the adipose tissue itself leads to a systemic pro-inflammatory state by promoting the secretion and release of pro-inflammatory mediators such as IL-6, IL-1β, TNF-α, leptin, and MCP-1, so that obesity per se is a risk factor for the development of EDy." (PMID 40005022, 2025). "Moreover, to assess the impact of obesity on the expression of IL1B in CC cells, we treated the HT-29 cell line with the adipocyte-conditioned medium (ACM) obtained from patients with obesity." (PMID 39305371, 2025). "Pro-inflammatory cytokines, including Interleukin 1 Beta (Il1b) and Interleukin 6 (Il6), are commonly found in WAT and are characteristic indicators of senescence.These cytokines are often associated with the development of insulin resistance in obesity." (PMID 40822955, 2025). "The imbalance of adipokines secreted by adipose tissue in obesity, especially elevated leptin levels, activates inflammatory pathways such as IL-1β and NF-κB, promoting articular cartilage degradation and synovial inflammation, which is an important mechanism in the development of OA." (PMID 40964689, 2025). "Other studies confirm the protective effect of education and income on the prevalence of depression and suggest that cytokines like IL-1β, TNFα, or the NF-κB pathway, which play a role in both obesity and depression, could explain the link." (PMID 40284257, 2025). "It has been demonstrated that combining aerobic and resistance exercise, as well as high-intensity interval training (HIIT), effectively reduces the expression of the NLRP3 gene and the proinflammatory cytokine IL-1β in individuals with obesity and type 2 diabetes." (PMID 40761804, 2025). "For this reason, we hypothesized that obesity and CC may influence the expression of IL-1β and its related molecules in the colon and visceral AT (VAT) from patients with obesity and CC." (PMID 39305371, 2025). "One of the supporting studies is that the inhibition of autophagy using small interfering RNA targeted to Atg7 increases proinflammatory gene expression (i.e., IL-1β, IL-6, and IL-8) in adipose tissue, thus suggesting that autophagy acts to suppress inflammation that is excessive during obesity." (PMID 41194853, 2025). "Muscle-derived IL-6 can inhibit the production of inflammatory cytokines such as TNF-α and IL-1β, while promoting secretion of anti-inflammatory cytokines like interleukin-10 (IL-10), thereby improving inflammatory profile in patients with sarcopenic obesity." (PMID 41141350, 2025). "Additionally, a significant intragroup reduction in IL-1β levels was observed in the overweight/pre-obesity population in the intervention group (p = 0.028)." (PMID 40430061, 2025). "In addition, a meta-analysis reported higher transcript levels of IL1B in AT samples obtained from patients with obesity compared with normal weight controls." (PMID 39305371, 2025). "Moreover, it has been documented the participation of macrophages in obesity‐associated angiogenesis in humanized mammary adipose tissue through CCL2 and IL‐1β." (PMID 40523654, 2025). "Upregulation of IL-1β has been found in both obesity and the tumor microenvironment." (PMID 40863244, 2025). "By contrast, the conditioned medium derived from cocultured activated EGCs treated with PA plus LPS displayed an increase in IL‐1β release, as compared with related control EGCs, thus indicating that, in the setting of obesity, activated EGCs represent the main source of IL‐1β." (PMID 39287080, 2025). "Obesity is closely associated with the development of insulin resistance (IR) and type 2 diabetes mellitus (T2DM), primarily due to dysfunctional adipose tissue expansion and the secretion of pro-inflammatory cytokines such as interleukin-1β (IL-1β)." (PMID 41154464, 2025). "The possible reason might be, sedentary life style of Ethiopian population leads to obesity and, in obese individual there is an excess formation of aromatase enzyme, leptin hormone and cytokines (TNFα and IL-1β)." (PMID 40811476, 2025).